CATSPERG (catsper channel auxiliary subunit gamma)
Description:
Auxiliary component of the CatSper complex, a complex involved in sperm cell hyperactivation. Sperm cell hyperactivation is needed for sperm motility which is essential late in the preparation of sperm for fertilization.
Synonyms: C19orf15; DKFZp434A1022; FLJ46353
Tractability: Antibody: its Gene Ontology location is reachable by antibodies, with high confidence; UniProt predicts a signal peptide or a membrane-spanning region.
Gene: Protein-coding gene on chromosome 19 (38,335,775 to 38,370,943, forward strand). Ensembl gene ENSG00000099338.
Subcellular location: Cell projection, cilium, flagellum membrane
Subcellular location (Human Protein Atlas): Mid piece; Principal piece; Predicted to be secreted
Pathways (Reactome):
Reproduction: Sperm Motility And Taxes
Gene Ontology:
Biological process: flagellated sperm motility; sperm capacitation; spermatogenesis
Cellular component: sperm principal piece; CatSper complex; motile cilium; plasma membrane
Genetic constraint (gnomAD): Loss-of-function variants: 110 observed, 147.55 expected, observed/expected ratio (o/e) 0.75, 90% interval 0.64 to 0.87. The upper end of that interval is the gene's LOEUF score, 0.87, which puts it in group 3 of 6, group 1 being the genes least tolerant of losing a copy. Missense variants: 1,294 observed, 1,555.1 expected, observed/expected ratio (o/e) 0.83, 90% interval 0.79 to 0.87. Synonymous variants: 586 observed, 620.84 expected, observed/expected ratio (o/e) 0.94, 90% interval 0.88 to 1.01.
Homologues: Orthologues: chimpanzee CATSPERG (99% identical), macaque CATSPERG (93% identical), dog CATSPERG (72% identical), pig CATSPERG (72% identical), mouse Catsperg1 (56% identical), mouse Catsperg2 (55% identical), rat Catsperg (54% identical).
Diseases named in the same sentence as CATSPERG in open-access papers:
CATSPERG is named in the same sentence as 3 diseases in open-access papers, as found by Europe PMC text mining. Sharing a sentence is not in itself a finding about the gene and the disease. The quoted sentences say what the papers report.
infertile (2 papers, 2019 to 2022). "In turn, estrogenic hypomethylated Alu sequences in the CMA3+ fraction of infertile patients were associated with an enrichment of genes involved in the internal male genital organs (BTO:0003096), the testis (BTO:0001363) and the male reproductive gland (BTO:0000080), including the CATSPERG gene." (PMID 36572941, 2022). "These genes play important roles in cell proliferation (RFX4, FOXM1, ASF1B), differentiation during spermatogenesis (CATSPERG, SPDYA, SPATA16, TSACC, TCP10L, DPY19L2) and motility of sperm cells during fertilization (DNAAF1); mutations in these genes may lead to infertility." (PMID 31671693, 2019).
Azoospermia (1 paper, 2025). Absence of any measurable level of sperm,whereby spermatozoa cannot be observed even after centrifugation of the semen pellet. "Recent bioinformatic analyses have identified CATSPERG as a hub gene significantly associated with spermatogenesis in non-obstructive azoospermia." (PMID 40943102, 2025).
CATSPERG also shares sentences with these, for which no sentence is quoted: cancer (1 paper).